CASP1 (caspase 1)
Diseases named in the same sentence as CASP1 in open-access papers (continued):
Sharing a sentence is not in itself a finding about the gene and the disease.
peritonitis (14 papers, 2009 to 2025). Inflammation of the peritoneum (tissue that lines the abdominal wall and covers most of the organs in the abdomen). "In vivo, intraperitoneal injection of hemozoin results in acute peritonitis, which is impaired in Nalp3-, caspase-1- and IL-1R-deficient mice." (PMID 19652710, 2009). "To investigate the in vivo role of RNH1 in inflammasome activation, we performed mouse models of caspase-1–dependent MSU-induced peritonitis and LPS-induced lethality." (PMID 35256513, 2022). "Neutrophil influx is impaired in an in vivo model of crystal-induced peritonitis in Nlrp3−/−, Asc−/−, Casp-1/Caspase-11−/−, and Il-1r−/− mice." (PMID 31803174, 2019). "Corroborating this, mouse models of monosodium urate (MSU)-induced peritonitis and lipopolysaccharide (LPS)-induced endotoxemia, which are dependent on caspase-1, respectively, show increased neutrophil infiltration and lethality in Rnh1−/− mice compared with wild-type mice." (PMID 35256513, 2022). "Caspase-1–deficient mice are resistant to LPS-induced lethality and MSU-induced peritonitis." (PMID 35256513, 2022). "Furthermore, the anti-inflammatory properties of 4-HAB were confirmed in a mouse model of uric acid crystals-mediated peritonitis by the reduced levels of neutrophil influx, IL-1β, active caspase-1, IL-6 and MCP-1 in lavage fluids." (PMID 31979265, 2020). "On the one hand, in experimental models caspase-1 activation contributes to mortality during Gram-negative sepsis, as caspase-1 deficient mice are protected against LPS-induced systemic inflammation and E. coli-induced lethal peritonitis." (PMID 21244670, 2011). "Furthermore, F240B exerted in vivo anti-inflammatory activity by reducing the intraperitoneal influx of neutrophils and the levels of IL-1β, active caspase-1, IL-6 and monocyte chemoattractant protein-1 (MCP-1) in lavage fluids in a mouse model of uric acid crystal-induced peritonitis." (PMID 33424855, 2020). "In air pouch inflammation and peritonitis mouse models, POVPC injection resulted in the production of caspase-1 (p10), IL-1β, and IL-18 in wild-type mice but not in NLRP3-deficient mice." (PMID 33534121, 2021).
pneumonia (14 papers, 2013 to 2026). An acute, acute and chronic, or chronic inflammation focally or diffusely affecting the lung parenchyma, caused by an infection in one or both of the lungs (by bacteria, viruses, fungi, or mycoplasma.). "CE reduced pro-inflammatory cytokine secretion, inhibited NLRP3, Caspase-1, and IL-1β protein expression, and upregulated key autophagy genes and proteins, thereby promoting autophagy and subsequently alleviating Hp-induced pneumonia damage in chicks." (PMID 41092609, 2025). "To further determine the role of neutrophils and macrophages in protecting against E. coli-induced pneumonia in Casp1-/- mice, we then used clodronate liposomes and an anti-Ly6G antibody to eliminate macrophages and neutrophils, respectively." (PMID 40359428, 2025). "The human macrophages in two-hit mice were unable to mount the activity of caspase-1 comparable to pneumonia mice." (PMID 40202049, 2025). "Moreover, LAA treatment reduced ASC, pro-caspase-1, caspase-1 p20, pro-IL-1β, mature-IL-1β, and IL-18 activation in the lungs of pneumonia mice in comparison with S. aureus-treated mice." (PMID 38803378, 2024). "The NLRP3/caspase-1 pathway is crucial to PM2.5-induced pneumonia." (PMID 37215119, 2023). "The results revealed that Vb treatment significantly suppressed mRNA levels of NLRP3, Caspase-1, and IL-1β in lung tissues of RSV-infected mice with pneumonia." (PMID 41349590, 2026).
pulmonary fibrosis (14 papers, 2015 to 2025). Chronic progressive interstitial lung disorder characterized by the replacement of the lung tissue by connective tissue, leading to progressive dyspnea, respiratory failure, or right heart failure. "Since NLRP3 is dispensable in various chronic inflammations, future study designs should consider using these knockout mice to carefully address the role of NLRP3 and caspase-1 in bleomycin-induced pulmonary fibrosis." (PMID 37958797, 2023). "Western blots of the whole lung extracts showed that the caspase-1 p20 subunit level was significantly higher in the pulmonary fibrosis model group compared to the control group seven days after bleomycin injection." (PMID 37958797, 2023). "Infiltration of inflammatory cells in the lung, production of mucus, lung fibrosis, and expression of caspase-1 or caspase-3 were suppressed in OVA-induced asthmatic animal treated with astaxanthin." (PMID 29160801, 2017). "The complete inactivation of the NLRP3 gene could better understand the NLRP3 inflammasome and caspase-1 in the pathogenesis of bleomycin-induced pulmonary fibrosis compared with pharmacological inhibition." (PMID 37958797, 2023). "Our study further found that YVAD, a caspase-1 inhibitor, could effectively alleviate bleomycin-induced pulmonary fibrosis both by downregulating the NLRP3 inflammasome and reducing the activity of EndoMT." (PMID 37958797, 2023). "Immunohistochemistry (IHC) staining of the lung tissues showed that the expression levels of the NLRP3 inflammasome and caspase-1 p20 were significantly higher in the pulmonary fibrosis model group compared to the control group seven days after bleomycin injection." (PMID 37958797, 2023). "Furthermore, recent studies have shown that BLM-induced pulmonary fibrosis increases protein levels of NLRP3 inflammasome components, including NLRP3, ASC, and Caspase-1, whereas NLRP3 deficiency results in recovery of lung fibrosis." (PMID 36432032, 2022). "Moreover, the activation of pyroptosis in PASMCs, which is related to pulmonary fibrosis induced by hypoxia, was alleviated by treatment with Caspase-1 inhibitors." (PMID 36284300, 2022). "Various studies have shown that activation of the NLRP3/caspase-1 pathway contributes to the inflammatory response through the onset of diseases such as airway inflammation and chronic obstructive pulmonary disease including pulmonary fibrosis." (PMID 34684415, 2021). "Moreover, astaxanthin effectively suppressed AHR, the infiltration of inflammatory cells in the lung, mucus hypersecretion, lung fibrosis, and the expression of caspase-1 and caspase-3." (PMID 29160801, 2017). "Recent studies have reported that Caspase-1 and NLRP3 levels in idiopathic pulmonary fibrosis and asthmatic patients are higher than those in healthy patients." (PMID 36432032, 2022). "Inhibition of NLRP3/Caspase-1/GSDMD-mediated pyroptosis largely reversed the injurious effects of hyperoxia, resulting in attenuated lung inflammation, improved alveolarization and pulmonary vascular development, and alleviated pulmonary fibrosis." (PMID 40486518, 2025). "Previous findings had reported that silica crystals induce the release of IL-1β and IL-18 and pulmonary interstitial fibrosis through the NLRP3 inflammasomes (tetracycline ameliorates silica-induced pulmonary inflammation and fibrosis via inhibition of caspase-1)." (PMID 36131930, 2022). "These authors also found that BLM-induced enhancement of lung collagen production was attenuated in mice lacking either NLRP3 or caspase-1, and that NLRP3– and ASC–deficient mice were resistant to BLM-induced skin and lung fibrosis." (PMID 26497260, 2015). "It was found that ROS generation induced by silica accelerated pyroptosis in macrophages via the NLRP3/caspase-1 signaling pathway, blocking macrophages’ pyroptosis by inhibiting the NLRP3 inflammasome or caspase-1 could reduce silica-mediated pulmonary fibrosis." (PMID 36248872, 2022).
pulmonary fibrosis (continued). "Similarly, in our previous work, we found that IL-1α was responsible for TGF-β release from idiopathic pulmonary fibrosis (IPF)-derived PBMCs in a caspase-4-, but not caspase-1-, dependent manner." (PMID 30930781, 2019).
hyperlipidemia (13 papers, 2016 to 2026). "The previous studies suggested that caspase-1 activation by hyperlipidemia leads to EC activation, caused pyroptosis of ECs, and increased ECs adhesion molecule production, which increases the adhesion of ECs to monocytes." (PMID 33339328, 2020). "On the other hand, in a mouse model of induced hyperlipidemia, the activation of caspase-1 was inhibited during early atherogenesis, facilitating the accumulation of sirtuin-1 in endothelial cells with consequent anti-inflammatory effects." (PMID 36359402, 2022). "In this study, swimming, as a treatment, reduced the expression of NLRP3, caspase-1, and IL-18, thereby indicating that exercise can act as a protective agent against hyperlipidemia-induced neuronal injury." (PMID 34409103, 2021). "Several studies have shown that caspase-1 promotes ECs activation and monocyte recruitment into the arterial intima in hyperlipidemia and lead to pyroptosis in ECs." (PMID 33339328, 2020). "Taken together, our results have demonstrated that hyperlipidemia and CKD significantly increase the plasma LDL-VLDL level and cytosolic LPS levels in the aorta; activate CASP4/11 more than CASP1; and increase 7 secretome cytokines and chemokines in plasma." (PMID 39024553, 2024). "Our data confirmed that increased hyperlipidemia-mediated inflammation activated HMGB1-TLR4 signaling, NLRP3 inflammasome formation, and upregulation of pyroptosis markers caspase-1, IL-1β, IL-18, and the pyroptosis executor GSDMD." (PMID 36829889, 2023). "Hyperlipidemia results in the upregulation of NLRP3, caspase-1, and IL-1β, and leads to pyroptosis in ECs." (PMID 33339328, 2020). "This clarifies that Lp(a), and not other serum components from patients with Lp(a) hyperlipidemia, is responsible for inducing caspase-1-mediated inflammasome activation in macrophages." (PMID 37293282, 2023). "Similarly, paeonol interacts with NLRP3 inflammasomes in a hyperlipidemic rat model has revealed that paeonol can reduce the levels of NLRP3, active caspase 1, and ASC to alleviate rat hyperlipidemia." (PMID 35303801, 2022). "Moreover, HLF could significantly reduce the levels of NLRP3, caspase-1, IL-1β, IL-6, IL-18, and TNF-α and increase the activities of plasma SOD, CAT, and GSH-PX, which suggested that HLF could effectively relieve the inflammatory response and oxidative stress induced by hyperlipidemia." (PMID 36425260, 2022).
lupus nephritis (13 papers, 2016 to 2025). Glomerulonephritis in the context of systemic lupus erythematosus. "We further demonstrated that citral inhibited ATP-induced caspase-1 activation and IL-1β production in LPS-primed J774A.1 macrophages and alleviated lupus nephritis in mice." (PMID 35967819, 2022). "In contrast, in the kidney, the expression of genes involved in pyroptosis, e.g. NLRP3 and CASP1 were significantly increased and TNFR1, RIPK1, RIPK3, CIAP1/2 and GPX4 were significantly decreased along the progression of lupus nephritis (LN)." (PMID 27811014, 2016). "Similarly, in the spontaneous lupus nephritis a mutant strain of NZM2328 mice with MCC950 administration showed significant inhibition in the expression of pro-caspase-1, p20 caspase-1, NLRP3 and IL-1β49." (PMID 35079027, 2022). "However, quercetin reversed the expression of NLRP3, ASC, caspase-1, N-GSDMD, and IL-1β induced by IL-33, indicating that quercetin can relieve inflammasome- and GSDMD-mediated pyroptosis in the cellular model of lupus nephritis." (PMID 36421424, 2022). "Another study suggested that down-regulation of BGN levels in models such as unilateral ureteral obstruction and lupus nephritis effectively reduces the expression levels of nucleotide-binding oligomerisation domain-like receptor protein 3 (NLRP3) and caspase-1 activity." (PMID 35069594, 2021). "Compared to those in SLE patients without renal damage, patients with lupus nephritis (LN) exhibited lower mRNA levels of NEK7, NLRP3, and ASC but higher levels of Caspase-1, IL-1b, and IL-18." (PMID 30202244, 2018).
malaria (13 papers, 2012 to 2024). Malaria is a serious and sometimes fatal disease caused by a parasite that commonly infects a certain type of mosquito which feeds on humans. "In the liver, inflammasome-mediated caspase-1 activation further enhances the control of Plasmodium, thus reducing the frequency and severity of clinical malaria." (PMID 39548522, 2024). "Nod-Like Receptor (NLR) P3/P12 dependent activation of caspase-1 is likely to be a key event in mediating systemic production of IL-1β with hypersensitivity to secondary bacterial infection during malaria." (PMID 31771607, 2019). "The higher amount of MyD88-IRF7 dependent type I IFN cytokines in pDCs of Il1r1−/−, Aim2−/−, Nlrp3−/−, and Casp1−/− mice at the early stage of YM infection facilitates anti-malaria adaptive immune response." (PMID 30470758, 2018). "Similar to mice, we observed a significantly increased frequency of circulating CD14+CD16−Caspase-1+ and CD14dimCD16+Caspase-1+ monocytes in peripheral blood mononuclear cells from febrile malaria patients." (PMID 24453977, 2014). "In this report, we describe a signature for the expression of inflammasome-related genes and caspase-1 activation in malaria." (PMID 24453977, 2014). "Here, we demonstrate that both in mouse and human malaria expression of inflammasome genes, caspase-1 activation and pyroptosis are induced in phagocytic cells." (PMID 24453977, 2014). "We conclude that NLRP12/NLRP3-dependent activation of caspase-1 is likely to be a key event in mediating systemic production of IL-1β and hypersensitivity to secondary bacterial infection during malaria." (PMID 24453977, 2014). "Another consequence of the decreased ROS generation during malaria would be the uncontrolled activation of caspase-1 and release copious amounts of active IL-1β by phagocytes, as previously reported in patients with chronic granulomatous disease (CGD)." (PMID 24453977, 2014). "We next studied caspase-1 activation and IL-1β release in peripheral blood mononuclear cells (PBMCs) from patients undergoing febrile malaria." (PMID 24453977, 2014). "In malaria patients, caspase-1, caspase-4, caspase-8 and GSDMD are activated in monocytes, which may contribute to the overall increased levels of IL-1β and immunopathogenesis during P. vivax and P. falciparum infections." (PMID 39548522, 2024). "High concentrations of immunocomplexes containing parasite DNA induce the AIM2 and NLRP3 inflammasome assembly, caspase-1 activation and IL-1β secretion in monocytes from infected patients, thereby stimulating systemic inflammation during acute malaria episodes." (PMID 39548522, 2024). "Also, Minocycline, sometimes called Minocin, is a broad-spectrum tetracycline antibiotic as well as a caspase 1 (CASP1) inhibitor while Chloroquine is a well-known anti- malaria drug." (PMID 22432004, 2012). "The work of Gazzinelli’s group used genetic and molecular approaches to demonstrate that CASP-8, CASP-1, mouse CASP-11, and its human ortholog CASP-4 were upregulated in monocytes from malaria patients and mice malaria models." (PMID 33672278, 2021). "As observed in the rodent malaria model, IFN-γ-priming of primary human monocytes mimics in vivo infection with Plasmodium and augments expression of pro-caspase-1, pro-IL-1β as well as IL-1β release induced by LPS stimulation." (PMID 24453977, 2014). "During malaria, AIM2 and NLRP3-induced CASP1-dependent inflammasome signaling induces the release of IL-1β in pDCs and activates IL-1 signaling, which induces negative regulator SOCS1 in a MyD88-TRAF3-IRF3-dependent manner and inhibits MyD88-IRF7-dependent type I IFN signaling in pDCs." (PMID 36214572, 2022). "Nlrp3 can however influence experimental cerebral malaria independently of caspase-1 and IL-1β, suggesting a non-classical role for Nlrp3 in malaria immunopathology." (PMID 23405174, 2013).
malaria (continued). "Notably, complement genes (C1QA, C1QB, C1QC), apoptotic genes (PDL1, PDL2, APOL1, APOL2, FAS), inflammatory caspases (CASP1, CASP5), TLR pathway genes (TLR1, TLR4, TLR5, TLR8), cytokines (IL6, IL10), and granzyme (GZMB) were among the genes upregulated during symptomatic malaria." (PMID 39161730, 2024).
acute respiratory distress syndrome (12 papers, 2012 to 2025). Progressive and life-threatening pulmonary distress in the absence of an underlying pulmonary condition, usually following major trauma or surgery. "The inflammasome-caspase-1 pathway plays a role in the onset of acute respiratory distress syndrome (ARDS), a diverse condition associated with elevated mortality rates." (PMID 40367557, 2025). "Furthermore, we found that intranasal administration of replication deficient adenoviral vectors in mice caused a high mortality in wild-type mice with symptoms of acute respiratory distress syndrome but the mice deficient in P2X7R or caspase-1 showed increased survival." (PMID 22558229, 2012). "In acute respiratory distress syndrome, NETs aggravate alveolar macrophage pyroptosis, and ASC foci, caspase-1, IL-1β, IL-6, and TNF-α are significantly associated with elevated NETs." (PMID 36430491, 2022). "Caspase-1 activation is not only a critical effector molecule in the development of acute respiratory distress syndrome (ARDS), but it is also a major contributor to the development of ALI." (PMID 36532040, 2022). "In our earlier studies, we found that MO-DCs are an important source of active caspase-1, IL-1β and have a pathogenic role in ECM and acute respiratory distress syndrome in malaria (MA-ARDS) models." (PMID 32929083, 2020). "Similarly, monocyte derived EVs encapsulated caspase-1 and their ability to induce apoptosis of pulmonary microvascular endothelial cells was observed in acute lung injury (ALI) and acute respiratory distress syndrome (ARDS)." (PMID 34685643, 2021).
Autoimmunity (12 papers, 2011 to 2025). The occurrence of an immune reaction against the organism's own cells or tissues. "Cleavage of cell surface receptors by caspase-1 is common, which raises its possible involvement in the initiation of autoimmunity to PLA2R causing exposure of immunogenic regions, such as the CysR epitope, to antigen processing by the immune system." (PMID 35858348, 2022). "Rac-1 is directly implicated in the activation of caspase-1, which is crucial for processing and secretion of the proinflammatory cytokines IL-1β and IL-18, promoting autoimmunity." (PMID 24147031, 2013). "Pharmacological or genetic inhibition of NLRP3 and caspase-1 improved renal function and suppressed autoimmunity in LN." (PMID 34867948, 2021). "Then, pro-IL-1B is activated by caspase 1 at the inflammasome, and both cytokines promote autoimmunity." (PMID 26064998, 2015). "Caspase-1 might play roles in the cross-talk between environmental exposure and development of autoimmunity." (PMID 32528469, 2020). "Thus, caspase-1 exerts a negative effect on the activation of IFN during DNA virus infection, and caspase-1 may suppress autoimmunity induced by the IFN pathway." (PMID 36560803, 2022). "In autoimmune POI models (for example, IFN-γ injury and ZP3 immunization), aberrant NF-κB signaling primes NLRP3–caspase-1–GSDMD-mediated granulosa-cell pyroptosis." (PMID 41465179, 2025). "To date, this caspase-1 inhibitor is the first to enter clinic development for the treatment of inflammatory and autoimmune conditions without any signs of toxicity." (PMID 29357878, 2018). "The contribution of the inflammasome and IL-1 to systemic autoimmunity remains unclear because while caspase 1 is required for pristane-induced autoimmunity, neither caspase 1 nor NALP3 is required for mercury-induced autoimmunity." (PMID 27014276, 2016).